UBE2V1 (ubiquitin conjugating enzyme E2 V1)
Diseases named in the same sentence as UBE2V1 in open-access papers:
UBE2V1 is named in the same sentence as 41 diseases in open-access papers, as found by Europe PMC text mining. Sharing a sentence is not in itself a finding about the gene and the disease. The quoted sentences say what the papers report.
breast carcinoma (10 papers, 2014 to 2024). "As this gene interacts with ubiquitin conjugating enzyme E2 variant 1 (encoded by UBE2V1, which was detected as a gene associated with OS), this UBE2V1 seems to be a novel molecular biomarker able to predict poor prognosis in breast cancer." (PMID 28544536, 2017). "Recently, Ube2v1 was reported to mediate matrix metalloproteinase-1 gene regulation through nuclear factor-кB and promote breast cancer metastasis." (PMID 30016968, 2018).
colorectal cancer (7 papers, 2018 to 2026). A primary or metastatic malignant neoplasm that affects the colon or rectum. "The present study aimed to investigate the expression of ubiquitin-conjugating enzyme E2 variant 1 (Ube2v1) in colorectal cancer (CRC) and its clinical significance." (PMID 37954522, 2023). "Remarkably, elevated expression levels of UBE2V1/2 correlate with improved survival rates in human colorectal cancer patients harboring oncogenic KRAS mutations, indicating that their upregulation could represent a promising therapeutic strategy." (PMID 41879050, 2026). "For instance, UBE2V1-mediated ubiquitination and degradation of Sirt1 promote colorectal cancer metastasis through epigenetic suppression of autophagy." (PMID 41446875, 2025). "For instance, in colorectal cancer, UBE2V1 forms heterodimers with UBC13, where UBC13 provides catalytic activity while UBE2V1 enhances affinity with E3 ligases such as TRAF6, promoting K63-linked ubiquitin chain synthesis." (PMID 41446875, 2025).
colon carcinoma (5 papers, 2017 to 2023). "Due to disagreements between two pathologists regarding the results of the immunohistochemistry of CRC and normal tissue, the present study decided to use TIMER and found that Ube2v1 expression was elevated in colon cancer tissues when compared with normal colon tissues." (PMID 37954522, 2023).
melanoma (4 papers, 2018 to 2025). A malignant, usually aggressive tumor composed of atypical, neoplastic melanocytes. "In melanoma, the interaction between UBE2V1 and UBC13 promotes tumor growth via the MEK/FRA1/SOX10 signaling pathway." (PMID 41446875, 2025).
diffuse large B-cell lymphoma (3 papers, 2014 to 2023). "Although concrete evidence for the role of Ube2v1 in cancer remains, some inhibitors targeting Ube2v1 pathway have been developed to treat some type of cancers, such as diffuse large B cell lymphoma cells." (PMID 30016968, 2018).
osteosarcoma (3 papers, 2017 to 2025). A usually aggressive malignant bone-forming mesenchymal neoplasm, predominantly affecting adolescents and young adults. "Additionally, UBE2V1 promotes osteosarcoma differentiation through Smurf1-dependent ubiquitination and subsequent degradation of Smad1." (PMID 41446875, 2025).
cervical cancer (2 papers, 2023 to 2024). A primary or metastatic malignant neoplasm involving the cervix. "In addition, UBE2V1 of aqueous humor expressed in the patients with Retinoblastoma (RB), similarly, high expression of UBE2V1 was correlated to the poor prognosis of patients with cervical cancer." (PMID 38795139, 2024).
colon adenocarcinoma (2 papers, 2018 to 2023). "The results showed that Ube2v1 expression was significantly elevated in colon adenocarcinoma and rectum adenocarcinoma tissues compared to normal tissues." (PMID 37954522, 2023).
lung adenocarcinoma (2 papers, 2022 to 2025). A carcinoma that arises from the lung and is characterized by the presence of malignant glandular epithelial cells. "For example, linc00426 may act as a ceRNA, which effectively suppresses the expression of miR-455-5p, thereby modulating the derepression of UBE2V1, a target gene of miR-455-5p in lung adenocarcinoma." (PMID 35578597, 2022).
bladder cancer (1 paper, 2024). "After treating bladder cancer cells with a UBE2V1/UBC13 inhibitor, both ubiquitination and expression of Lin28a were affected, and UBC13 was found to interact with Lin28a, indicating that UBE2V1/UBC13 regulates the ubiquitination of Lin28a." (PMID 39237880, 2024). "We further validated the interaction between UBE2V1 and UBC13 in bladder cancer cells." (PMID 39237880, 2024).
colorectal tumor (1 paper, 2026). "Furthermore, Uev1A and UBE2V1/2 also counteract oncogenic Ras-driven tumorigenesis in diploid cells, suppressing the overgrowth of germline tumors in Drosophila and human colorectal tumor xenografts in nude mice, respectively." (PMID 41879050, 2026).
diabetic nephropathy (1 paper, 2024). "In renal fibrosis due to diabetic nephropathy, miR-27b-3p and miR-1228-3p bind to the ubiquitin-binding E2 enzyme variant (UBE2v1) 3'-UTR and inhibit UBE2v1-mediated lysine 63-linked ubiquitin chain formation." (PMID 39113708, 2024).
fibrosis (1 paper, 2019). the formation of excess fibrous connective tissue in an organ or tissue in a reparative or reactive process. "We validated the up‐regulation of UBE2V1, BNIP3L mRNAs, RP11‐128N14.5 lncRNA, TGFB2/TGFB2‐OT1 coding/lncRNA in patients with NAS ≥ 5 (vs NAS ≤ 4) and the up‐regulation of HBA2 mRNA, TGFB2/TGFB2‐OT1 coding/lncRNA in patients with Fibrosis stages = 3‐4 (vs F = 0‐2)." (PMID 31169972, 2019).
gestational diabetes mellitus (1 paper, 2025). "A transcriptomic profiling analysis of trophoblast isolated from gestational diabetes mellitus (GDM) defined 8 ubiquitin-conjugating enzymes (UBE) splice variants (UBE2D3 variants 1, 3, 4, 5, 6, 7, 9 and UBE2V1 variant 4) are associated with increased maternal fasting plasma glucose." (PMID 40410732, 2025).
HIV-1 infection (1 paper, 2017). The type species of lentivirus and the etiologic agent of acquired immunodeficiency syndrome (AIDS). "Our replication of CD101 Ig-like variants showed an HR for HIV-1 infection of 4.3 (95% CI = [2.1–8.9], p = 6.4x10-5); and replication of association of UBE2V1 rs6095771 with HIV-1 acquisition risk showed an HR of 6.4 in women (95% CI = [2.1, 19.1], p = 9.5x10-4)." (PMID 29108000, 2017). "Hence, these variants or others in CD101 and UBE2V1 could have a substantial impact on the population-based HIV-1 infection risk." (PMID 29108000, 2017).
lymph node metastasis (1 paper, 2023). "The results of immunohistochemistry revealed that Ube2v1 expression was associated with lymph node metastasis, and a trend towards an association with stage/invasion (pT stage) was observed." (PMID 37954522, 2023). "In addition, the Ube2v1 expression level was closely associated with the presence of lymph node metastasis and exhibited a trend towards stage/invasion association (pT stage)." (PMID 37954522, 2023). "Ube2v1 expression was associated with lymph node metastasis in patients with CRC (P<0.05)." (PMID 37954522, 2023).
pancreatic cancers (1 paper, 2023). "Thus, we demonstrated that the role of LINC00460 in pancreatic cancer is achieved by regulating its downstream molecules, miR-4689, and further mediates the expression of UBE2V1." (PMID 37786443, 2023). "CCK-8 and colony formation assays indicated that down-regulation of UBE2V1 reduced the proliferation ability of pancreatic cancer cell lines, while overexpression of LINC00460 could partly rescue this effect." (PMID 37786443, 2023). "In addition, we identified that LINC00460 and UBE2V1 were significantly positively correlated in pancreatic cancer." (PMID 37786443, 2023). "Proliferation and metastasis of pancreatic cancer may therefore be mediated by the LINC00460/miR-4689/UBE2V1 axis." (PMID 37786443, 2023). "However, the function and mechanism of UBE2V1 in pancreatic cancer are unknown." (PMID 37786443, 2023). "Mechanistically, LINC00460 plays the role of oncogene by acting as a sponge of miR-4689, activating its downstream target, UBE2V1, and sequestering USP10 to promote the proliferation and metastasis of pancreatic cancer." (PMID 37786443, 2023). "Downregulation of UBE2V1 significantly inhibits the proliferation and metastasis of pancreatic cancer, while overexpression of LINC00460 can partially reverse the inhibitory effect of UBE2V1." (PMID 37786443, 2023).
Rett syndrome (1 paper, 2020). A severe neurodevelopmental disorder affecting the central nervous system. "Moreover, reduced UBE2V1 levels were observed in the cerebellum and blood of a mouse model of Rett syndrome, a rare neuropsychiatric disorder." (PMID 33076555, 2020).
teratocarcinoma (1 paper, 2016). A germ cell tumor characterized by the presence of an embryonal carcinoma component and a teratoma component. "Examples include the HHLA1-OC90 fusion transcript which is present only in teratocarcinoma cell lines and the Kua-UBE2V1 fusion protein which localized to cytoplasm while UBE2V1 is a nuclear protein." (PMID 27296891, 2016).
cancer (14 papers, 2010 to 2025). A tumor composed of atypical neoplastic, often pleomorphic cells that invade other tissues. "Previous studies have implicated UBE2V1 as a potential oncoprotein across multiple cancer types." (PMID 41446875, 2025). "The TMEM189 and UBE2V1 genes are neighboring genes that are normally expressed separately and are thought to be targets in different cancer types." (PMID 40724830, 2025). "To investigate the expression pattern of UBE2V1 during tumorigenesis, we conducted differential analysis based on the Genotype-Tissue Expression (GTEx), The Cancer Genome Atlas (TCGA) program, and GEO databases." (PMID 41446875, 2025). "Ube2v1 complexes with Ube2n and activates the nuclear factor κB (NF-κB) signaling pathway, which is involved in the regulation of cancer." (PMID 37954522, 2023). "Pan-cancer analysis demonstrated that UBE2V1 was enhanced in the majority of cancer types." (PMID 41446875, 2025). "Nevertheless, the role of UBE2V1 in cancers including LUAD and the mechanisms involved are still largely unknown." (PMID 33311443, 2020). "Nevertheless, the role of Ube2v1 in autophagy and cancer including CRC and the mechanisms involved are still largely unknown." (PMID 30016968, 2018). "The present study thus examined Ube2v1 expression in CRC tissues, and identified associations between Ube2v1 expression and the clinical and pathological characteristics of patients with CRC in order to determine the clinical significance of Ube2v1 expression in this type of cancer." (PMID 37954522, 2023). "Ube2v1 interacts with Ubc13 through non-covalent binding to mediate formation of K63-linked polyubiquitin chains (K63Ub chains), which activate the NF-κB pathway to regulate inflammation and cancer occurrence." (PMID 37954522, 2023).
tumor (13 papers, 2014 to 2025). "Ubiquitin-conjugating E2 enzyme variant 1 (Ube2v1), one member of ubiquitin-conjugating E2 enzyme variant proteins, has been controversially suggested as both a candidate oncogene or a tumor suppressor." (PMID 30016968, 2018). "Based on these findings, we constructed a predictive nomogram integrating UBE2V1 expression with clinical variables (including gender, age, tumor grade, and stage) to estimate 1-, 3-, and 5-year OS probabilities." (PMID 41446875, 2025). "The subcutaneous tumorigenesis assay demonstrated that UBE2V1 knockdown markedly inhibited tumor growth, with marked reductions in both tumor volume and weight." (PMID 41446875, 2025). "In this study, we demonstrated that the hypoxic tumor microenvironment induces the up-regulation of UBE2V1 in HCC, mediated through direct transcriptional activation by HIF-1α binding to an HRE in the UBE2V1 promoter region." (PMID 41446875, 2025). "Assessment of stem-like properties showed a marked reduction in tumor sphere formation in UBE2V1 knockdown cells." (PMID 41446875, 2025). "Collectively, these results demonstrate that the hypoxic tumor microenvironment of HCC induces UBE2V1 up-regulation by promoting HIF-1α binding to the P6 region (−208 to −201 bp, GGTCGTGC) of its promoter." (PMID 41446875, 2025). "Specifically, UBE2V1 mRNA levels were significantly elevated in HCC tumor tissues compared to paired adjacent normal controls, with box plot validation confirming consistent overexpression across independent cohorts." (PMID 41446875, 2025). "In CRC patients, Ube2v1 expression is elevated in tumor samples especially in advanced TNM staging and correlated with poorer survival of patients." (PMID 30016968, 2018). "And Ube2v1 expression is increased significantly in the early stage for the acquisition of immortality of tumor cells." (PMID 30016968, 2018). "In vivo studies using orthotopic mouse xenograft models of CRC showed that Ube2v1 promotes tumor growth and metastasis." (PMID 30016968, 2018). "We present a critical role of Ube2v1 in tumor growth and metastasis of CRC in vivo and in vitro." (PMID 30016968, 2018). "Inconsistently, Ube2v1 can also function as a tumor suppressor by protecting cells from DNA damage." (PMID 30016968, 2018). "In contrast, UBE2V1 overexpression significantly increased tumor growth, while systemic administration of PX-478 suppressed tumor development in a dose-dependent manner, confirming that the pro-tumorigenic effects of UBE2V1 in HCC are mediated through HIF-1α activation." (PMID 41446875, 2025). "Ubiquitin conjugating enzyme E2 variant 1 (UBE2V1), a core component of the ubiquitin-conjugating enzyme family, plays a critical role in the UPS and has been implicated in autophagy, protein homeostasis, and the activation of signaling pathways that drive tumor progression and reproductive aging." (PMID 41446875, 2025). "Given its significance in the process of tumor progression, Linc00426 may act as a promising predictive biomarker for LUAD, and proper regulation of the Linc00426-miR-455-5p-UBE2V1 axis may be a novel synergistic strategy for inhibiting the process of tumor progression." (PMID 33311443, 2020). "In this study, analyses of TCGA and GEO datasets, along with validation in clinical specimens, revealed significant up-regulation of UBE2V1 in HCC tissues, which correlates with advanced tumor stage, tumor grade, and lymph node metastasis." (PMID 41446875, 2025). "Collectively, these data establish a direct UBE2V1–VHL interaction in HCC cells and suggest its functional relevance in governing tumor progression." (PMID 41446875, 2025). "UBE2V1 was frequently overexpressed in HCC tissues, where its expression levels strongly correlated with advanced tumor stage and poor prognosis." (PMID 41446875, 2025). "Overexpression of UBE2V1 was frequently detected in HCC tissues and correlated strongly with advanced tumor stage and unfavorable patient prognosis." (PMID 41446875, 2025).
tumor (continued). "Ube2v1 promoted migration and invasion of CRC cells in vitro and tumor growth and metastasis of CRC cells in vivo." (PMID 30016968, 2018). "More importantly, IHC and Western blot (WB) analyses of paired tumor specimens revealed a significant up-regulation of UBE2V1 protein abundance in HCC tissues compared to adjacent nontumor tissues." (PMID 41446875, 2025).
UBE2V1 also shares sentences with these, for which no sentence is quoted: COVID-19 (4 papers); breast tumor (2); infection (2); viral infection (2); acute myeloid leukemia (1); cardiac disease (1); colorectal adenocarcinoma (1); Creutzfeldt Jakob disease (1); diabetes (1); Ewing sarcoma (1); hepatocellular carcinoma (1); hypertrophic cardiomyopathy (1); metastatic colorectal cancer (1); metastatic tumors (1); neuroblastoma (1); oral carcinoma (1); rectum adenocarcinoma (1); renal fibrosis (1); respiratory failure (1); retinoblastoma (1).